NOA1 (nitric oxide associated 1)
Description:
Involved in regulation of mitochondrial protein translation and respiration. Plays a role in mitochondria-mediated cell death. May act as a scaffolding protein or stabilizer of respiratory chain supercomplexes. Binds GTP.
Synonyms: C4orf14; MGC3232; hAtNOS1; hNOA1; MTG3; mAtNOS1
Tractability: Small molecule: a structure with a bound ligand is known. Antibody: UniProt places it where antibodies can reach, with high confidence. PROTAC: ubiquitination databases record sites on it; its protein half-life has been measured.
Gene: Protein-coding gene on chromosome 4 (56,962,876 to 56,977,623, reverse strand). Ensembl gene ENSG00000084092.
Subcellular location: Mitochondrion inner membrane
Subcellular location (Human Protein Atlas): Mitochondria
Gene Ontology:
Molecular function: GTP binding; protein binding; RNA binding; RNA folding chaperone
Biological process: mitochondrial small ribosomal subunit assembly; mitochondrion organization; mitochondrial ribosome assembly; RNA folding
Cellular component: matrix side of mitochondrial inner membrane; mitochondrion; mitochondrial inner membrane; mitochondrial matrix
Genetic constraint (gnomAD): Loss-of-function variants: 37 observed, 56.48 expected, observed/expected ratio (o/e) 0.66, 90% interval 0.5 to 0.86. The upper end of that interval is the gene's LOEUF score, 0.86, which puts it in group 3 of 6, group 1 being the genes least tolerant of losing a copy. Missense variants: 866 observed, 862.62 expected, observed/expected ratio (o/e) 1, 90% interval 0.95 to 1.06. Synonymous variants: 384 observed, 362.22 expected, observed/expected ratio (o/e) 1.06, 90% interval 0.97 to 1.15.
Homologues: Orthologues: chimpanzee NOA1 (99% identical), macaque NOA1 (94% identical), dog NOA1 (79% identical), pig NOA1 (78% identical), guinea pig NOA1 (77% identical), rat Noa1 (75% identical), mouse Noa1 (75% identical), rabbit NOA1 (74% identical), tropical clawed frog noa1 (49% identical), zebrafish noa1 (46% identical), Caenorhabditis elegans noa-1 (31% identical), Drosophila melanogaster CG10914 (31% identical). Paralogues in human: GNL2 (12% identical), GNL1 (12% identical), LSG1 (12% identical), GNL3 (11% identical), GNL3L (10% identical), MTG1 (9% identical).
Diseases named in the same sentence as NOA1 in open-access papers:
NOA1 is named in the same sentence as 12 diseases in open-access papers, as found by Europe PMC text mining. Sharing a sentence is not in itself a finding about the gene and the disease. The quoted sentences say what the papers report.
breast carcinoma (1 paper, 2024). "We constructed a risk model based on the expression levels of these RBPs and found that ADAT2, C2orf15, SRP72, PAICS, RBMS3, APOBEC3G, NOA1, and ACO1 could be used for risk assessment in terms of breast cancer prognosis." (PMID 38783078, 2024). "By further analysing above EMT-related RBPs and AS in breast cancer tissues in TCGA, it was found that the expression levels of ADAT2, C2orf15, SRP72, PAICS, RBMS3, APOBEC3G, NOA1, ACO1 and the AS of TNC and COL6A3 were significantly correlated with the prognosis of breast cancer patients." (PMID 38783078, 2024).
hepatoma (1 paper, 2025). "MS results showed that NOA1 might be a potential target of WTAP in hepatoma cells." (PMID 39744575, 2025). "In a nutshell, WTAP affected NOA1 to activate the GPX4 expression and reduce the Fe2+, improving GSH/GSSH levels to suppress ferroptosis of hepatoma cells, which may promote the occurrence and development of HCC." (PMID 39744575, 2025).
lung carcinoma (1 paper, 2022). "With a relatively loose threshold (p < .2), the genes Dhx16, Upf2, Denr, Notch3, Dyrk2, Sec61a1, Hmmr, and Noa1 were reversed in at least three treatment protocols and most of these genes were reported to be related to COPD or lung cancer." (PMID 35993327, 2022).
prostatitis (1 paper, 2025). An infectious or non-infectious inflammatory process affecting the prostate gland. "Our analysis revealed two Tier 2 genes (NOA1 and ELAC2) for BPH, two Tier 3 genes (TRMU and SFXN5) for prostatitis, and six Tier 3 genes (MRPL24, NDUFS6, PUS1, NBR1, GLOD4, and PCBD2) for PCa." (PMID 40919435, 2025). "We revealed two Tier 2 genes (NOA1 and ELAC2) and one Tier 3 gene (ACAT1) for BPH, two Tier 3 genes (TRMU and SFXN5) for prostatitis, and six Tier 3 genes (MRPL24, NDUFS6, PUS1, NBR1, GLOD4, and PCBD2) for PCa." (PMID 40919435, 2025).
infection (3 papers, 2013 to 2023). The state of being infected such as from the introduction of a foreign agent such as serum, vaccine, antigenic substance or organism. "In any case, the Arabidopsis mutant noa1 is not only impaired in NO production but is also more susceptible to infection by diverse pathogens, including Pseudomonas syringae, Colletotrichum orbiculare and Sclerotinia sclerotiorum." (PMID 24058365, 2013). "Nitric oxide-associated protein 1 (NOA1) was involved in various abiotic stress responses and required for plants to resist pathogen infection." (PMID 38138993, 2023). "This is in accordance with the infection phenotypes of the NO-deficient mutants, nia1 nia2 and noa1, collectively suggesting that NO is not involved in mediating immune responses to biotrophic pathogens." (PMID 24058365, 2013).
bacterial infection (1 paper, 2013). "Although the noa1 mutant is defective in a plastidic GTPase rather than NOS, it shows reduced NO levels after bacterial infection or elicitor treatment." (PMID 24058365, 2013).
tumor (1 paper, 2020). "Genes CBX3, RCC1, TMOD3, and NOA1 (Cluster A) and TOP1, PDCD5, and THRAP3 (Cluster B) were upregulated for both datasets in PCa tissue vs. normal gland or normal adjacent to tumor tissue." (PMID 32640729, 2020).
NOA1 also shares sentences with these, for which no sentence is quoted: age-related macular degeneration (1 paper); COVID-19 (1); Genetic disorders of (1); invasive breast carcinoma (1); iron deficiency (1).